ATF3 (activating transcription factor 3)
Diseases named in the same sentence as ATF3 in open-access papers (continued):
Sharing a sentence is not in itself a finding about the gene and the disease.
hepatocellular carcinoma (32 papers, 2011 to 2026). A malignant tumor that arises from hepatocytes. "Low levels of ATF3 expression have been associated with poor overall survival in patients with hepatocellular carcinoma (HCC)." (PMID 40361912, 2025). "In conclusion, this study presents hitherto undocumented evidence that DSF/Cu treatment upregulates ATF3 expression in hepatocellular carcinoma cells." (PMID 41438581, 2026). "The impact of ATF3 on hepatocellular carcinoma (HCC) cell behavior, encompassing proliferation, invasion, migration, and colony formation, was investigated to delineate its role, given its reported dual functions in HCC pathogenesis." (PMID 39996726, 2025). "ATF3-mediated ferroptosis has been shown to play a key role in a variety of diseases such as gastric cancer, hepatocellular carcinoma, acute kidney injury, among others." (PMID 38244586, 2024). "SEH1L promotes hepatocellular carcinoma progression by inhibiting ferroptosis, while its silencing induces ferroptosis via the ATF3/HMOX1/GPX4 axis, suppressing tumor growth." (PMID 39315094, 2024). "Brusatol (BRU) inhibits hepatocellular carcinoma (HCC) growth by inducing ATF3-mediated ferroptosis, highlighting its potential as an effective therapeutic agent for HCC." (PMID 39315094, 2024). "Lipid desaturation-associated endoplasmic reticulum (ER) stress inhibits MYCN expression via upregulating the transcriptional repressor ATF3 in hepatocellular carcinoma cells." (PMID 33614505, 2020). "Acyclic retinoid dampens MYCN gene expression and suppresses cell proliferation of MYCN-overexpressed hepatocellular carcinoma cells, at least in part by ER stress-induced ATF3 signaling pathway." (PMID 33614505, 2020). "In vitro and in vivo assays were performed to investigate the functional role of ATF3 in hepatocellular carcinoma." (PMID 30376856, 2018). "Binding of ATF3 to the STAT3 promoter for gene inactivation has also been shown in human hepatocellular carcinoma." (PMID 30455690, 2018). "Using MAPK-specific inhibitors reversed the increase in ATF-3 expression in GS-002-treated hepatoma cells." (PMID 24222778, 2013). "This study indicated that SEH1L siliencing could induce ferroptosis and suppresses hepatocellular carcinoma (HCC) progression via ATF3/HMOX1/GPX4 axis." (PMID 39095556, 2024). "We examined the effects of ATF3 on Ripk3 expression using H4IIE rat hepatoma cells." (PMID 36690638, 2023). "In hepatocellular carcinoma and esophageal squamous cell carcinoma, ATF3 expression was lower than that in normal adjacent tissues and could suppress tumor growth." (PMID 33816467, 2021). "However, overexpression of ATF3 increases cyclin D1 mRNA expression in the Hepa 1–6 mouse hepatoma cells." (PMID 32922364, 2020). "However, overexpression of ATF3 increases DNA synthesis and cyclin D1 mRNA expression in the Hepa 1–6 mouse hepatoma cells." (PMID 32922364, 2020). "In addition, ATF3 has been reported to mediate the suppression of cell viability in human hepatocellular carcinoma cells (HepG-2)." (PMID 25494848, 2014). "Of note, opposing effects of ATF3 on cyclin D1 expression have been previously documented: ATF3 binds to AP-1 motif and activates cyclin D1 in mitogen-stimulated mouse hepatoma cells, whereas it binds to ATF/CRE site and represses cyclin D1 in mouse fibroblasts stimulated by serum." (PMID 22046379, 2011). "In the context of hepatocellular carcinoma (HCC), ATF3 predominantly functions as a tumor suppressor, with downregulated expression levels observed in HCC patients compared to healthy individuals." (PMID 39996726, 2025).
hepatocellular carcinoma (continued). "Saikosaponin A (SsA) induces ferroptosis in hepatocellular carcinoma (HCC) cells by inhibiting SLC7A11 and activating ATF3 through endoplasmic reticulum stress, highlighting its potential as a therapeutic ferroptosis inducer in HCC treatment." (PMID 39315094, 2024). "Finally, we indicated that Linc01612 could interact with miR-494 to upregulate the expression of ATF3 in hepatocellular carcinoma." (PMID 35541917, 2022). "However, the expression pattern and exact role of ATF3 in the development and progression of hepatocellular carcinoma (HCC) remain unclear." (PMID 33407456, 2021). "The stress response gene ATF3, has been shown to activate erastin-induced ferroptosis by repressing amino acid antiporter system Xc– and could serve as a prognostic biomarker in hepatocellular carcinoma." (PMID 34276794, 2021). "ATF3 level is low in human hepatocellular carcinoma (HCC) tissues, and there was a decreased ATF3 protein level in patients with capsule invasion." (PMID 32922364, 2020). "In hepatocellular carcinoma, ATF3 expression is lower in patients with advanced HCC and capsule invasion." (PMID 30376856, 2018). "Next, we wanted to understand whether GS-002 can induce ATF-3 expression in human hepatoma cells." (PMID 24222778, 2013). "SA stimulates the production of activating transcription factor 3 (ATF3), which is essential for SA-induced ferroptosis and inhibition of SLC7A11 in hepatocellular carcinoma." (PMID 38738178, 2024). "In hepatocellular carcinoma (HCC), ATF3 cooperates with SPTBN1 and SMAD3 to inhibit STAT3 activity, thereby suppresses HCC development." (PMID 30455690, 2018). "Studies have found that activation of ATF3 may regulate the expression or activity of GPX4, ultimately affecting the occurrence of ferroptosis and inhibiting the progression of hepatocellular carcinoma." (PMID 41550926, 2025). "A previous study discovered that CDCA8 could inhibit the ATF3 tumor suppressor and activate the AKT/β-catenin signalling pathway to promote the development of hepatocellular carcinoma." (PMID 36358852, 2022). "In this study, overexpression of ATF-3 enhanced GS-002-induced apoptosis in hepatoma cells, indicating that ATF-3 has a negative role in cell proliferation and is a key mediator in GS-002-induced apoptosis." (PMID 24222778, 2013). "Interestingly, PPG did not induce ATF-3 expression compared to GS-002 in hepatoma cells." (PMID 24222778, 2013).
cardiac hypertrophy (31 papers, 2011 to 2025). "The findings of this study indicate that ATF3 overexpression in cardiomyocytes is associated with cardiac hypertrophy." (PMID 41453996, 2025). "In the cardiovascular system, it is significant in modulating cardiac remodeling, as mice with ATF3 deficiencies showed cardiac hypertrophy, dysfunction, and fibrosis under overload pressure." (PMID 35282347, 2022). "ATF3 was activated by various environmental stress signals and was associated with the pathogenesis of various diseases, including cancer, cardiac hypertrophy, infection, and inflammation." (PMID 34966780, 2021). "(2011) first reported that ATF3 deficiency promotes myocardial hypertrophy and fibrosis in heart failure caused by excessive stress load, suggesting that ATF3 has a cardioprotective function." (PMID 32670070, 2020). "On the other hand, ATF3‐deficient mice are protected from cardiac hypertrophy and bleomycin‐induced skin fibrosis." (PMID 29363258, 2018). "Data also showed up-regulation of about 180 genes including Tgfb2, Ace, Atf3, Ctgf, Angpt14, Col9a2, Wisp2, Nppa, Nppb, and Actn1 that are linked to cardiac muscle contraction, cardiac hypertrophy, cardiac fibrosis and myocardial injury." (PMID 27548259, 2016). "The functional importance of ATF3 in cardiac hypertrophy is somewhat controversial.ATF3 deficiency (a loss-of-function approach) has been shown to promote cardiachypertrophy in an aortic banding pressure overload model." (PMID 23874609, 2013). "ATF3 deficiency promoted cardiac hypertrophy, dysfunction and fibrosis after 4 weeks of AB compared to the wild type (WT) mice." (PMID 22053207, 2011). "Here, we investigated the effects of ATF3 deficiency on cardiac hypertrophy using in vitro and in vivo models." (PMID 22053207, 2011). "We show that ATF3 deficiency in mice promotes cardiac hypertrophy, dysfunction and fibrosis in response to pressure overload, suggesting a crucial role for ATF3 in modulating cardiac remodeling." (PMID 22053207, 2011). "In this study, we demonstrated that ATF3 deficiency worsened cardiac hypertrophy induced by pressure overload in vivo and by Ang II in vitro." (PMID 22053207, 2011). "Additionally, ATF3 overexpression in adult mice causes ventricular hypertrophy, cardiac dysfunction, and fibrosis." (PMID 41453996, 2025). "Interestingly, we identified four genes, Btg2, Egr1, Fos, and Atf3, associated with cardiac hypertrophy, in overlapping DEGs between the upregulated DEGs in PAH versus control groups and the downregulated DEGs in PAH/αKO versus PAH groups." (PMID 36736425, 2023). "On the one hand, ATF3 deficiency was reported to result in cardiac hypertrophy and fibrosis." (PMID 37759510, 2023). "Compared to wild-type siblings, Tg(myl7:ATF3) zebrafish exhibited significant pathophysiological changes, including cardiac hypertrophy and features resembling hypertrophic cardiomyopathy." (PMID 41453996, 2025). "The findings of this study provide evidence that QL mitigates cardiac hypertrophy through the miR-382-5p/Activated Transcription Factor 3 (ATF3) axis." (PMID 39332150, 2024). "Mice were injected with AAV9-NC, AAV9-miR-382-5p mimic or AAV9-si-ATF3 adenovirus through the tail vein after intragastric QL, and then injected with Ang-II to induce myocardial hypertrophy.." (PMID 39332150, 2024). "This present study provides novel evidence that QL alleviates myocardial hypertrophy and cardiac dysfunction through the miR-382-5p/ATF3 axis." (PMID 39332150, 2024). "As demonstrated in this study, QL inhibits Ang-II-stimulated cardiomyocyte hypertrophy by miR-382-5p/ATF3 axis, but the mechanism of QL's protection against cardiac hypertrophy needs further study." (PMID 39332150, 2024). "ATF3, a member of the cAMP response element-binding protein/ATF family, has been linked to heart hypertrophy." (PMID 36901722, 2023).
cardiac hypertrophy (continued). "Upon weaning and doxycycline removal, ATF3 is expressed in cardiomyocytes leading to heart hypertrophy, fibrosis and cardiac dysfunction and cancer progression." (PMID 37759510, 2023). "In this study, we show that tumor-bearing ATF3 transgenic mice display decreased cardiac hypertrophy and fibrosis levels compared to tumor-free mice." (PMID 37759510, 2023). "ATF3 overexpression in cardiomyocytes is sufficient to induce heart hypertrophy and cardiac fibrosis, resulting in cardiac contractile dysfunction." (PMID 37759510, 2023). "ATF3 plays a dual role in cardiac remodeling, and both ATF3 knockdown and overexpression in adult mice resulted in cardiac hypertrophy and dysfunction in response to pathological stimulation." (PMID 36675183, 2023). "Research has shown that, by regulating the miR-145-5p/ATF3 axis, circNFIX can attenuate pressure overload-induced cardiac hypertrophy." (PMID 36901722, 2023). "Two recent studies have shown that circNfix and RNA circ_0001006 can alleviate and promote myocardial hypertrophy in mice by targeting the miR‐145‐5p/activating transcription factor 3 (ATF3) and miR‐214‐3p/PAK6 pathways, respectively." (PMID 37002786, 2023). "Yet the tumor promotion phenotype was identified in multiple other mice models, such as those reflecting myocardial infarction (MI), pressure overload (TAC), and heart hypertrophy (ATF3 transgene)." (PMID 37628775, 2023). "Secondly, the clinical significance of circNfix, miR-145-5p and ATF3 during the development of cardiac hypertrophy should be explored in the future." (PMID 34468254, 2021). "In conclusion, circNfix attenuated pressure overload-induced cardiac hypertrophy by regulating the miR-145-5p/ATF3 axis." (PMID 34468254, 2021). "Consistent with the results of those studies, it was found herein that circNfix and ATF3 were positively correlated in patients with cardiac hypertrophy, indicating the key role of ATF3 in the progression of cardiac hypertrophy." (PMID 34468254, 2021). "In the present study, circNfix was found to attenuate pressure overload-induced cardiac hypertrophy by regulating the miR-145-5p/ATF3 axis." (PMID 34468254, 2021). "The present findings enhanced our understanding of the biological effect of circNfix, miR-145-5p and ATF3 in the progression of cardiac hypertrophy." (PMID 34468254, 2021). "circNfix attenuated pressure overload-induced cardiac hypertrophy by regulating the miR-145-5p/ATF3 axis." (PMID 34468254, 2021). "Overexpression of ATF3 in heart results in rapid ventricle hypertrophy and ATF3 KO mice display reduced heart hypertrophy." (PMID 27548259, 2016). "We further show that ATF3 overexpression leads to a decreased rate of protein synthesis, a marker for cardiac hypertrophy, and is characterized with activation of a suppressor of inflammation, NF-κB, as well as with activation of a survival factor Nkx-2.5." (PMID 25136830, 2014). "In a complementary approach, ATF3 KO mice displayed a lower levelof heart hypertrophy in the same pressure overload model." (PMID 23874609, 2013). "In summary, ectopicexpression of ATF3 is sufficient to promote cardiac hypertrophy and exacerbatesthe deleterious effect of chronic pressure overload; conversely, ATF3 deletionprotects the heart." (PMID 23874609, 2013). "To further confirm the effect of ATF3 on cardiac hypertrophy, we used an in vitro model with Ang II (1 μM) in cultured neonatal mouse cardiomyocytes." (PMID 22053207, 2011). "To evaluate the effect of ATF3 on cardiac hypertrophy, we performed the AB surgery or a sham operation on ATF3-KO mice and WT littermates." (PMID 22053207, 2011). "Mice with cardiac-specific over-expression of ATF3 exhibited atrial enlargement and cardiac hypertrophy in a previous report; however, our results demonstrated that ATF3 deficiency promotes pathological hypertrophy." (PMID 22053207, 2011).
cardiac hypertrophy (continued). "Our results suggested that ATF3 plays a crucial role in the development of cardiac hypertrophy via negative regulation of the MEK-ERK1/2 and JNK pathways." (PMID 22053207, 2011). "This beneficial outcome was consistent with two additional heart failure mouse models: the activating transcription factor 3 (ATF3) transgenic mouse model for cardiac hypertrophy and transverse aortic constriction (TAC) surgery, a pressure overload mouse model mimicking aortic stenosis." (PMID 41322654, 2025). "Secondly, the downstream mechanism of ATF3 affecting cardiac hypertrophy is still unclear." (PMID 39332150, 2024). "QL, miR-382-5p, and ATF3 should be explored clinically for their roles in cardiac hypertrophy." (PMID 39332150, 2024). "Thus, it seems that ATF3 transgene expression in cardiomyocytes initiates a harmful sequence of events that result in cardiac hypertrophy, fibrosis, and dysfunction." (PMID 39634266, 2024). "In addition to GATA, MEF2 and NFAT families, other transcription factors, such as UBF1 86, ATF3 87, T-Cdk9 88, XBP1 89, MITF 90, HSF1 91, C/EBP 92, KLF11 93 and KLF5/BTEB2 94 have been implicated in regulating cardiac hypertrophy." (PMID 39239522, 2024). "In addition, circNFIX counters heart hypertrophy by indirectly targeting activating transcription factor 3 (ATF3) in cardiomyocytes through binding to the microRNA miR-145-5p." (PMID 36901722, 2023). "Two additional cardiac hypertrophy models: a genetically modified mouse model overexpressing the activating transcription factor 3 (ATF3) in cardiomyocytes, and a phenylephrine (PE) infusion representing a hypertension mouse model, were used to study tumor growth in our lab." (PMID 38139195, 2023). "The role of ATF3 in cardiac hypertrophy is a matter of debate." (PMID 37759510, 2023). "Significantly, mice with cardiomyocyte ATF3 expression develop cardiac hypertrophy and fibrosis." (PMID 37759510, 2023). "ATF3 overexpression in cardiac tissues can promote myocardial hypertrophy and fibrosis." (PMID 36704356, 2022). "First, the interaction between ATF3 and cardiac hypertrophy remains unclear, and additional rescue experiments should be performed." (PMID 34468254, 2021). "Ectopic expression of ATF3 was sufficient to promote cardiac hypertrophy." (PMID 34054926, 2021). "We found that circNfix could attenuate Ang II–induced cardiac hypertrophy in vitro and TAC-induced cardiac hypertrophy in vivo by regulating the miR-145-5p/activating transcription factor 3 (ATF3) axis." (PMID 34468254, 2021). "Using EMSA, we demonstrated in the current study that ATF3 overexpression increased DNA binding activity of NF-κB and Nkx-2.5, while the binding activity of AP-1, transcription factor mainly related to pathological cardiac hypertrophy, remained unchanged." (PMID 25136830, 2014). "In a very recent study, cardiac overexpression of ATF3 in mice was sufficient to promote cardiac hypertrophy and exacerbate the deleterious effect of chronic pressure overload, while ATF3 knockout mice displayed less cardiac hypertrophy in the pressure overload model." (PMID 25136830, 2014). "The exposure of adult ATF3 expressing mice to PE infusion (a pressure overload model)resulted in an additional increase in the ventricle-to-body–weight ratio and heartfunction deterioration along with the promotion of heart hypertrophy." (PMID 23874609, 2013). "Taken together, our data support themodel that ATF3 promotes cardiac hypertrophy." (PMID 23874609, 2013). "Our study provides new insight into the pathogenesis of cardiac remodeling and may have important implications for the development of strategies for the treatment of cardiac hypertrophy and heart failure through targeting ATF3." (PMID 22053207, 2011).